TLR3 (toll like receptor 3)
Diseases named in the same sentence as TLR3 in open-access papers (continued):
Sharing a sentence is not in itself a finding about the gene and the disease.
diabetes (22 papers, 2009 to 2024). "Specifically, infection with a diabetogenic islet β cell-tropic strain of coxsackievirus (CB4) results in diabetes protection under reduced MDA5 signaling conditions while reduced TLR3 function retains diabetes susceptibility." (PMID 34804036, 2021). "Key immune pathways involving TLR2, TLR3, and PD-1/PD-L1 were shown to modulate the balance between innate and adaptive immunity, with smoking, aging, diabetes, and obesity also impacting critical cytokine responses." (PMID 39456722, 2024). "These mice developed diabetes when injected with polyI:C (Toll-like receptor 3 agonist) and spontaneous diabetes when co-expressing RIP-hB7.1 along with CD8+ and CD4+ T cell responses that largely overlap." (PMID 35498419, 2022). "TLR2, TLR3, and TLR4 are frequently implicated in the pathogenesis of diabetes, T1D-related vascular complications, and CS-induced inflammation and COPD." (PMID 36013497, 2022). "In diabetes resistant C57BL/6 mice, MDA5 and TLR3 signaling are both required to prevent diabetes following infection with a pancreatropic virus encephalomyocarditis virus strain D (EMCV-D)." (PMID 34804036, 2021). "The reduction of cutaneous REG3A, possibly as a consequence of decreased IL-17-induced IL-33 caused by hyperglycaemia, will therefore lead to excessive production of TLR3-mediated pro-inflammatory cytokines observed in diabetes after skin trauma." (PMID 27830702, 2016). "It has been reported that activation of TLR3 in PBMCs of patients with diabetes can increase the expression of IL-6." (PMID 23946637, 2013). "BBDR rats treated with Kilham rat virus (KRV) and polyinosinic:polycytidylic acid (pIC, a TLR3 agonist) develop diabetes at nearly 100% incidence by ~2 weeks." (PMID 24147110, 2013). "To better understand how immune pathologies like IFN-I responses that result from MDA5 and TLR3 signaling influence T1D development, we challenged heterozygous NOD mice that retained MDA5 and TLR3 function with known diabetes and IFN-I inducers like coxsackievirus B4 (CB4)." (PMID 34804036, 2021). "Mice with deficiency of Tlr3, a virus recognition molecule that senses dsRNAs in the endosomal compartment, showed an increased viral titer in the pancreas and the presence of EMCV antigen mainly in the islets, resulting in the development of diabetes." (PMID 32727064, 2020). "Moreover, bone marrow (BM) chimeras containing Tlr3−/− hematopoietic cells and wild type (WT) stroma developed diabetes after EMCV-D infection, whereas chimeras containing WT hematopoietic cells and Tlr3−/− stroma were protected." (PMID 32727064, 2020). "CD11c-positive DCs and possibly other Tlr3-positive myeloid cells may play a role in the Tlr3-mediated control of EMCV-D-induced diabetes." (PMID 32727064, 2020). "Here we observed that defective REG3A expression may impair wound healing in diabetes through the exacerbation of TLR3-mediated inflammation." (PMID 27830702, 2016). "To investigate whether SR-A plays a crucial role in the transport of dsRNA to TLR3, we studied diabetes progression in NOD and SR-A−/− NOD mice in the presence or absence of poly(I∶C) treatment." (PMID 25343451, 2014). "To investigate whether SR-A plays a crucial role in TLR3 recognition of dsRNA, we studied diabetes progression in SR-A−/− NOD or wild type NOD mice in the presence or absence of poly(I∶C) treatment." (PMID 25343451, 2014). "Here, we asked whether TLR3 plays a role in the response to coxsackievirus B4 (CB4), a prevalent human pathogen that has been associated with pancreatitis, myocarditis and diabetes." (PMID 19122812, 2009). "For example, miR-146a was significantly upregulated during CVB3-infected mice and potentially modulated TLR3 and TRAF6 genes that control β cell activity in diabetes-induced inflammation." (PMID 39697323, 2024). "In the PCC group, there was a correlation between duration of diabetes and neutrophil TLR1 (r = −0.730, p = 0.04), TLR3 (r = 0.766, p = 0.03) and TLR5 (r = 0.843, p = 0.01) mRNAs." (PMID 28794498, 2017).
diabetes (continued). "Here the authors report that REG3A inhibits TLR3-driven inflammation in skin wounds, and show that REG3A is reduced in models of diabetes, which exacerbates inflammation in diabetic wounds." (PMID 27830702, 2016). "When treated with the parvovirus Kilham rat virus (KRV) and a TLR3 agonist, polyinosinic:polycytidylic acid (pIC), BBDR rats develop diabetes at a high rate (~100%), with consistent kinetics (~2 weeks)." (PMID 24147110, 2013). "For example, elevated normalized kidney weight and Agt RNA expression, along with decreased Tlr3 and Vegfa RNA expression, demonstrated that diabetes, but not CVB4 exposure, was responsible for their differential expression." (PMID 34835482, 2021). "While TLR2 and TLR9 knockout mice show little development of diabetes, a defect of TLR3 appears to be without impact and, as we show here, deficiency in TLR4 causes enhancement of the disease process." (PMID 24086519, 2013). "In stark contrast to the importance of IL-12 in TLR4 mediated DC maturation and subsequent induction of diabetes, IL-12 was not required in TLR3 mediated DC induction of autoimmunity." (PMID 21931625, 2011). "It is also striking that diabetes protection by TLR3 stimulation required the presence of IL-4 which was not the case for TLR4-induced protection." (PMID 20628601, 2010). "Decorated with a high concentration of pattern recognition receptors, i.e., TLR3/4, RIG-I, MDA-5, and with IL-1R1, and especially vulnerable to inflammatory destruction, the β-cell undergoes apoptosis in response to inflammation, metabolic control derails and diabetes develops." (PMID 33162939, 2020). "It was reported that diabetes development was completely prevented in MyD88−/− NOD mice, whereas the deletion of TLR3 could not suppress diabetes development in NOD mice." (PMID 25343451, 2014).
HIV-1 infection (22 papers, 2011 to 2025). The type species of lentivirus and the etiologic agent of acquired immunodeficiency syndrome (AIDS). "It is known that stimulation of macrophages through TLR3 or TLR4 reduces their susceptibility to HIV-1 infection, but the mechanism is not well understood." (PMID 23028330, 2012). "The CT genotype for the TLR3 rs3775291 C/T variant was more frequent in the group of patients with an advanced stage of HIV-1 infection when compared to the control group, which may influence the risk of infection progression." (PMID 40831704, 2025). "TAR within EVs was shown to increase viral pathogenesis through the down-regulation of apoptosis, increased susceptibly to HIV-1 infection, and activation of TLR3 to subsequently stimulate the production of pro-inflammatory cytokines within uninfected recipient cells." (PMID 35203372, 2022). "TLR-3 recognizes double stranded RNA, and it has shown to inhibit HIV-1 infection through the induction of type 1 interferon and inflammatory cytokine/chemokine." (PMID 37226084, 2023). "This research showed that a common TLR3 allele confers an immunological advantage that can protect against HIV-1 infection and proposed the potential use of stimulation of TLR3 levels in HIV-1 immunotherapy." (PMID 32578708, 2020). "Although our current data demonstrates the involvement of TLR10 in HIV-1 infection, the existence of such synergy between TLR10 and TLR3 in an HIV-1 infection cannot be dismissed and requires further future investigation." (PMID 30930906, 2019). "This study indicates that a TLR3-induced miRNA exerts an anti-HIV-1 effect by targeting several HIV-1 dependency factors to inhibit HIV-1 infection." (PMID 29426337, 2018). "The stimulation of TLR3, 7/8 and 9 controls more efficiently HIV-1 infection in the uterus than in other compartments, while TLR4 stimulation does not have a major impact." (PMID 28953320, 2017). "TLR3 has been described to induce antiviral activity during acute HIV-1 infection, including upregulation of antiviral micro-RNAs in macrophages." (PMID 28253319, 2017). "The innate immune response through TLR3, 4, or 7/8 each controlled HIV-1 infection of primary human macrophages." (PMID 21904615, 2011). "In the context of HIV-1 infection, the stimulation of DCs is reliant on TLR-3 activation." (PMID 38397105, 2024). "In the case of HIV-1 infection, activation of dendritic cells is dependent on TLR-3 activation." (PMID 37226084, 2023). "In vitro studies revealed that IFN-λ can upregulate cellular anti-HIV-1 factors through JAK-STAT signaling pathway and significantly inhibited HIV-1 infection; TLR-3 activated by Poly I:C can induce multiple anti-HIV-1 factors and inhibit HIV-1 infection of macrophages." (PMID 28186978, 2017). "TLR3 activation in macrophages has been shown to prevent HIV-1 infection, suggesting that the activation of the TLR3 signaling pathway might help macrophages to resist subsequent infection with similar viruses." (PMID 25106750, 2014). "Ongoing virus replication despite ART has been proposed to take place during HIV-1 infection supporting the possibility that TLR3 stimulation by HIV-1 could take place during ART treatment." (PMID 24558379, 2014). "As an example, agonists for TLR3, TLR7, TLR8, and TLR9 have been shown to be capable of inhibiting HIV-1 infection and induced IFN-α-stimulated gene expression in PBMCs in vitro." (PMID 38994942, 2024). "We found that GPR15 expression was up-regulated ex vivo on CD4+ T cells in two out of eleven HIV-1 patients, that HIV-1 infection can upregulate GPR15 in PM1 T cells and that TLR3 triggering by dsRNA up-regulated GPR15 expression on CD4+ T cells." (PMID 24558379, 2014). "The stimulation of polyinosinic-polycytidylic acid [poly (I:C)] and bacterial lipopolysaccharide (LPS), the ligands for toll-like receptor 3 (TLR3) and TLR4, respectively, are known to decrease HIV-1 infection in monocyte-derived macrophages (MDMs), but the mechanism was unclear." (PMID 29426337, 2018).
HIV-1 infection (continued). "It will be of interest to study further whether HIV-1 infection truly results in activation of RIG-1 and TLR3 signaling in monocytes in vivo and whether this has an impact on viremia and disease progression." (PMID 28253319, 2017). "The trend observed indicating reduced TLR3 expression on splenic CD4 T cells upon HIV-1 infection could additionally contribute to the lack of HIV-1 RNA recognition." (PMID 30867315, 2019). "Moreover, the compound, either alone or in combination with TLR3 and TRL4 agonists, elicits the expression of cytokines, chemokines, and co-stimulatory molecules that are involved in counteracting HIV-1 infection, in activating and recruiting APCs, and in shaping adaptive immunity." (PMID 24473338, 2014). "Thus, among CD4-positive T cells, the TLR3 induced up-regulation of GPR15 expression is largely specific for gut homing CD4+ T cells and might broaden the target cell availability during HIV-1 infection in the gut." (PMID 24558379, 2014). "We identified a subset of four miRNAs that were significantly up-regulated in cells stimulated through TLR3 and TLR4 but not through TLR7 and could potentially play a role in modulating susceptibility to HIV-1 infection in this system." (PMID 23028330, 2012). "A recent study shows that HIV-1 infection of lymphoid tissue is affected differently by different TLR ligands, so we investigated whether HIV-1 infection of purified human peripheral blood lymphocytes (PBL) is affected by exposure to ligands of TLR3, 4, or 7/8." (PMID 21904615, 2011). "Stimulation with viral ligands Poly(I:C) (TLR3) and R848 (TLR 7/8), which efficiently activated immature vaginal LCs, did not result in increased HIV-1 infection compared to unstimulated LCs." (PMID 36841916, 2023). "We also demonstrate that miR-155 is selectively up-regulated upon TLR3/4- but not TLR7-stimulation, and that specific inhibition of miR-155 partially restores HIV-1 infection in poly(I∶C)-stimulated MDMs." (PMID 23028330, 2012). "We found that ligation of TLR3, 4, or 7/8 on MDM blocked R5 HIV-1 infection of MDM but not of peripheral blood lymphocytes." (PMID 21904615, 2011). "At this point, HIV-1 infection resulted in a trend toward suppression of Toll-like receptor 3 (TLR3) protein expression on splenic but not peripheral CD4 T cells, whereas peripheral TLR7 and TLR9 protein expression was elevated after HIV-1 infection of both CD4 T cells and macrophages." (PMID 30867315, 2019).
systemic lupus erythematosus (22 papers, 2010 to 2025). An autoimmune multi-organ disease typically associated with vasculopathy and autoantibody production. "In a cohort of Danish females, the upregulation of TLR-3 was associated with systemic lupus erythematosus (SLE)." (PMID 37508529, 2023). "Mammalian endosomal TLRs, specifically TLR7, TLR8, TLR9 and TLR3, are crucial in the development of systemic lupus erythematosus (SLE) in humans." (PMID 40976999, 2025). "More recently, vitamin D3 has shown to reduce TLR3, 7, and 9 gene expression in cultured PBMCs from systemic lupus erythematosus patients." (PMID 34068701, 2021). "Another study found that repeated stimulation by polyI:C injected to lupus-prone MRLlpr/lpr mice aggravated nephritis by chronic TLR3 activation on glomerular mesangial cells and antigen-presenting cells." (PMID 32719713, 2020). "In contrast, TLR3 expression was observed in glomerular mesangial cells in lupus model mice, i.e., MRLlpr/lpr mice, although TLR3, 7 and 9 expressed in infiltrating macrophages in these mice with nephritis." (PMID 30103522, 2018). "It is of note that mesangial cells from female animals express more TLR3 copies and secrete more IL-6 production upon TLR3 activation, providing another explanation for gender disparity in lupus." (PMID 29650017, 2018). "TLR-3 and -9 are expressed in human synovial tissue from RA patients and in peripheral blood cells in active systemic lupus erythematosus." (PMID 20937083, 2010). "However, in a murine model of systemic lupus erythematosus, particularly in kidneys, the expression of TLR-3 was also described specifically in MCs and infiltrating antigen-presenting cells." (PMID 36233224, 2022). "Furthermore, polymorphisms in TLR3, TLR7 and TLR9 genes have been associated with lupus patients in some populations and a number of in vivo and in vitro studies have strongly implicated a number of TLRs to play a role in the pathogenesis of lupus." (PMID 27846842, 2016). "Prolonged TLR3 may lead to autoimmune reaction and aggravates lupus pathogenesis." (PMID 22952664, 2012). "Similarly, TRIM21, an autoantigen associated with Systemic Lupus Erythematosus (SLE), negatively regulates type I IFN production driven by TLR3, TLR7, and TLR9." (PMID 40495154, 2025). "Female New Zealand Black/WF1 mice with systemic lupus erythematosus (SLE) and SS-like lesions expressed TLR3 in the salivary gland, particularly in duct epithelial and acinar cells." (PMID 33803026, 2021). "For subjects with HPV infection, levels of TLR3 and TLR7 were significantly lower in lupus patients compared with controls." (PMID 22513098, 2012). "For subjects with HPV infection (Groups 1 and 3), TLR3 and TLR7 levels were significantly lower in lupus patients compared with controls." (PMID 22513098, 2012). "In addition, since nucleic acids are important elements in apoptotic cells that are required for the abnormal cytokine response by lupus monocytes, TLRs (specifically TLR3, 7, 8 and 9) and their downstream pathways may also play important role as mediators of this response." (PMID 21423726, 2011). "For instance, PBMCs obtained from patients with systemic lupus erythematosus that were treated with 50 nM of VitD3 express lower levels of TLR3, TLR7, and TLR9 compared to non-treated PBMCs, as observed in this study." (PMID 34634046, 2021).
liver fibrosis (19 papers, 2010 to 2025). "The experimental data from both types of mice helped us to explore the role of TLR3 in liver fibrosis caused C. sinensis and the mechanism of host-parasite interaction." (PMID 37167198, 2023). "It is noteworthy that TLR3 deficiency caused severe clonorchiasis with lower survival quality, higher liver damage, and more severe liver fibrosis." (PMID 37167198, 2023). "Toll-like receptor-3 deficiency in HSCs contributed to decreased IL-17A production by γδ T cells, as well as liver fibrosis." (PMID 27824548, 2016). "We found that an important result of TLR3 deficiency was a significantly higher number of infected worms, which may be another important reason for more severe liver damage and liver fibrosis in TLR3-/- mice infected with C. sinensis." (PMID 37167198, 2023). "The role of TLR3 in liver diseases promptes us to investigate whether it is involved in the liver fibrosis process caused by C. sinensis." (PMID 37167198, 2023). "In a CCl4-induced mouse model of liver fibrosis, exosome-mediated activation of Toll-like Receptor 3 in HSCs during the early stages of liver injury promoted the progression of liver fibrosis by enhancing the production of IL-17A from Gamma Delta T cells." (PMID 39995661, 2025). "This study suggests that TLR3-based treatments have a great potential for applications in C. sinensis and other parasitic liver fibrosis." (PMID 37167198, 2023). "Here, the TLR3 signaling pathway, cytokine expression and liver fibrosis were examined in C. sinensis-infected wildtype (WT) and TLR3-/- mice." (PMID 37167198, 2023). "Kupffer cells and liver stellate cells (HSCs) which are found in the liver, express TLRs (such as TLR3) and are crucial in the development of liver fibrosis and HCV infection." (PMID 38173795, 2023). "To explore the TLR3-mediated mechanism of C. sinensis-induced liver fibrosis, we isolated CsEVs and examined the phosphorylation of inflammatory pathways and cytokine expression in mouse BECs stimulated with CsEVs." (PMID 37167198, 2023). "Our results show that patients with a more severe necroinflammatory process (METAVIR A2 score), which is usually characteristic of a faster progression of liver fibrosis, have higher transaminase levels and lower intrahepatic TLR3 and IFNL3 expressions." (PMID 34207750, 2021). "In CCl4-induced acute liver injury and early stage liver fibrosis, exosomes released by hepatocytes bind to TLR3 and activate HSCs to produce IL-17A, which promotes the production of IL-17A by hepatic γδ T cells to aggravate liver fibrosis." (PMID 33869241, 2021). "Liver fibrosis and IL-17A production by γδ T cells were both significantly attenuated in toll-like receptor (TLR)-3 KO mice compared with wild-type mice." (PMID 27824548, 2016). "In this review, we summarize the role of TLR3 in liver injury, inflammation, regeneration, and liver fibrosis, and discuss the implication of TLR3 in the pathogenesis of human liver diseases including viral hepatitis and autoimmune liver disease." (PMID 20936107, 2010). "Liver fibrosis in C. sinensis-infected WT and TLR3-/- mice was observed using Masson staining." (PMID 37167198, 2023). "In summary, a new role for TLR3 in controlling C. sinensis-induced liver fibrosis was identified." (PMID 37167198, 2023). "Evidence suggests that TLR3 is involved in the progression of liver fibrosis." (PMID 37167198, 2023). "Activation of TLR3 in HSCs has been demonstrated to exacerbate liver fibrosis." (PMID 36200827, 2023). "In a mouse model of liver fibrosis, exosomes were shown to activate toll-like receptor 3 in HSCs." (PMID 35625625, 2022). "TLR-3 poly I : C-linked induces activation of NK42 cells which destroy HSCs and IFN-gamma production by inducing apoptosis and inhibition of HSCs proliferation, leading to liver fibrosis restrain." (PMID 22114589, 2011).